RUNX1 (RUNX family transcription factor 1)
Diseases named in the same sentence as RUNX1 in open-access papers (continued):
Sharing a sentence is not in itself a finding about the gene and the disease.
cancer (continued). "We first found that YTHDC1 mRNA expression was downregulated in cancer tissues compared with nontumor tissues, and there was a positive association between YTHDC1 and miR-30d and a negative association between YTHDC1 and RUNX1, SLC2A1, HK1." (PMID 34021267, 2021). "We find that RUNX1/RUNX1T1 controls RNA-isoform expression by preventing alternative initiation of transcription and, thus, directly link an initiating and driving oncogenic event with the recently discovered pervasive regulation of transcription through alternative promoters in cancer cells." (PMID 33483506, 2021). "For example, MYB is required for both RUNX1 transcriptional activity, for the ability of a chimeric RUNX1 fusion oncogene to transform hematopoietic cells, and RUNX1 can cooperates with MYB to activate ectopic targets through novel MYB binding sites in cancers." (PMID 25587024, 2014). "Furthermore, to determine whether RUNX1 protein expression is also increased in CRC, qRT-PCR and Western blotting were performed in 61 pairs of fresh samples and in 12 pairs of fresh samples, including cancers and matched adjacent normal tissues or independent normal tissues." (PMID 31370857, 2019). "Two transcriptional regulators, including RUNX1 and CTCF, were not identified as driver cancer genes." (PMID 29485617, 2018). "Using PPI analysis, the critical pathway of functional genes was found involved in the hematopoietic cell lineage and transcriptional misregulation in cancer, including HOXA10, MEIS1, FLT3, CD14, PROM1, RUNX2, and RUNX1 (data not shown), indicating the dominant roles of HOXA and MEIS1 in MLL-R ALL." (PMID 36276286, 2022).
hematological malignancies (82 papers, 2010 to 2026). "The most significantly hypermethylated CpGs were frequently linked to genes involved in the pathogenesis of hematological diseases, including RUNX1, BRD4, SRSF2, SETBP1 and TNFSF10." (PMID 40319310, 2025). "RUNX1-FPDMM is a hereditary disorder that increases the risk of developing hematologic malignancies, particularly MDS and AML." (PMID 41458504, 2025). "Similar to what is observed in sporadic hematologic malignancies, additional acquired genetic events cooperate with the hereditary RUNX1 variant to progress the manifestation of the malignant phase." (PMID 38203823, 2024). "Nevertheless, DS individuals show a disproportionately higher predisposition to specific hematological malignancies, and RUNX1 overexpression has been proposed to contribute to such dysregulation." (PMID 37670378, 2023). "Little is known about the role of the RUNX1 gene in the development of secondary somatic mutations in patients with IBMFSs and how these mutations lead to hematological malignancies." (PMID 35765406, 2022). "Despite recent research having demonstrated the strong association of RUNX1 mutations in a variety of hematological malignancies, it is unclear how RUNX1 mutations contribute to the pathogenesis of hematological malignancies in IBMFS." (PMID 35765406, 2022). "This review aims to study the role of RUNX1 mutations in the pathogenesis of hematological malignancies in patients with IBMFS." (PMID 35765406, 2022). "Previous studies have shown that RUNX1 is one of the most frequently mutated genes in hematological malignancies." (PMID 35765406, 2022). "A recent bioinformatics study identified recurrent mutations in REs that affect gene function, including RUNX1 and are connected to hematological malignancies development." (PMID 36005134, 2022). "The similarity of germline CEBPA, DDX41 and RUNX1 mutations associated with haematological diseases warrants further study, such as the long time to follow-up with the family members." (PMID 35279121, 2022). "Pathogenic germline variants affecting RUNX1 are associated with qualitative and/or quantitative platelet defects, and predispose to hematologic malignancies." (PMID 35884491, 2022). "This review has highlighted the importance of studying the role of somatic RUNX1 mutations in the pathogenesis of hematological malignancies and the potential implications in the development of oncological therapies." (PMID 35765406, 2022). "According to recently published data, somatic mutations of RUNX1 were observed in various types of hematological malignancies." (PMID 35765406, 2022). "RUNX1 is also critical for the differentiation of lymphocytes, and its aberrant expression has been linked with various hematological malignancies." (PMID 35565298, 2022). "These cases illustrate the importance of secondary events in the development and progression of RUNX1-FPD-associated hematologic malignancies." (PMID 35884491, 2022). "For example, RUNX1 has been demonstrated to be one of the most frequently mutated genes in several hematological malignancies." (PMID 36034894, 2022). "Pathogenic loss-of-function RUNX1 germline variants cause autosomal dominantly-inherited familial platelet disorder with predisposition to hematologic malignancies (RUNX1-FPD)." (PMID 35884491, 2022). "RUNX1 germline mutations are associated with familial platelet disorders (FPD) with predisposition to hematological malignancies." (PMID 32782381, 2021). "Mutations and translocation of RUNX1 frequently occur in hematological malignancies and are proposed to underlie chemotherapeutic resistance." (PMID 34414175, 2021). "The transcription factor AML1 (RUNX1) represents a crucial regulator of physiologic hematopoietic differentiation and is recurrently mutated in a wide variety of hematologic malignancies." (PMID 34331016, 2021).
hematological malignancies (continued). "The high incidence of RUNX1 mutations in multiple types of hematologic malignancies provides strong evidence for its essential function in blood lineage development." (PMID 33434583, 2021). "Given the high complexity in RUNX1 expression and function, its deregulation is commonly associated with haematopoietic diseases." (PMID 32323916, 2020). "In particular, RUNX1 is essential for the ontogeny of the hematopoietic system and alterations of RUNX1 have been associated with a broad spectrum of hematological malignancies." (PMID 33025905, 2020). "Patients with genetic mutations in RUNX1 have a predisposition to develop hematological malignancies where the genetic information can be used to monitor the patients' hematological parameters very closely." (PMID 31275945, 2019). "Mutations in RUNX1 have been shown to result in either haploinsufficiency or can act in a dominant-negative manner, the latter resulting in an increased risk of hematological malignancies." (PMID 26102509, 2015). "Mutations and rearrangements on RUNX1 are key drivers of hematological malignancies." (PMID 37670378, 2023). "Considering this, it could be hypothesized that these specific hematopoietic diseases in MCM10-deficient human patients were caused by an alteration of RUNX1 expression." (PMID 37437546, 2023). "It is suspected that additional RUNX1 mutations may play a role in the pathogenesis of hematological malignancies in IBMFS." (PMID 35765406, 2022). "The frequency of RUNX1 mutations in various types of hematological malignancies." (PMID 35765406, 2022). "However, mutations of RUNX1 are detected in hematological malignancies frequently and less frequently in some solid tumors." (PMID 36429115, 2022). "The RUNX1 gene is frequently mutated in various hematological malignancies." (PMID 33353065, 2020). "RUNX1 (Runt-related transcription factor 1), a central member of the Runt family, has traditionally been recognized as a master regulator of hematopoietic development and lineage specification, with its dysregulation closely linked to various hematologic malignancies." (PMID 41463011, 2025). "Further research may lead to the discovery of biomarkers for early detection of leukemic progression, promoting a deeper understanding of molecular mechanisms by which RUNX1 mutations contribute to hematological malignancies and the development of new therapeutic interventions." (PMID 35765406, 2022). "The selected articles were used to evaluate the clinical and molecular characteristics of RUNX1 mutation in various types of hematological malignancies, the mechanisms of pathogenesis caused by RUNX1 mutations, and potential therapeutic strategies for hematological malignancies with RUNX1 mutations." (PMID 35765406, 2022). "This is consistent with studies showing that RUNX1 contributes to hematologic malignancies by enhancing abnormal proliferation and survival." (PMID 40990016, 2025). "Given its substrate targets (e.g. BAF155 and RUNX1) and gene targets (e.g. BMI-1 and ID2), CARM1 and phospho-CARM1 appear to play a pivotal role in hematologic malignancies with the JAK2-V617F mutation, and likely in other settings as well." (PMID 38649367, 2024). "For example, germline variants in RUNX1, ANKRD26, and ETV6 all predispose to thrombocytopenia and hematologic malignancies." (PMID 38203823, 2024). "It is thought that the accumulation of various variants, such as the CDC25C biallelic RUNX1 variant, and the TET2 variant, causes progression to preleukemic clones and eventually leads to the development of hematologic malignancies." (PMID 38203823, 2024).
hematological malignancies (continued). "RUNX1 activities in normal megakaryopoiesis and hematopoietic stem cell maintenance, and their relations to hematological diseases, have been extensively studied for many years and, therefore, will not be covered in the present review." (PMID 37670378, 2023). "Runt-related transcription factor 1 (RUNX1) has been widely studied in hematological diseases and plays an important role in the occurrence and development of hematological diseases." (PMID 37760803, 2023). "The RUNX1 transcription factor plays multifaceted functions in hematopoietic diseases and solid cancers, behaving in a context-dependent manner." (PMID 37697370, 2023). "Although this process has been described for RUNX1 in hematological malignancies, to our knowledge, ours is the first description of a key role for the RUNX1 transcription factor in response to chronic high glycemic dietary stress." (PMID 36079709, 2022). "Transcription factors activated in both liver and muscle include Irf8, Jun, Egr1, Cebpa, Foxl2, the hypoxia-inducible factor Hif1a, and Runx1, a key regulator in hematological malignancies." (PMID 35865523, 2022). "Because the somatic mutation of RUNX1 was first identified in MDS and AML, RUNX1 has become known to be one of the most frequently mutated genes in a variety of hematological malignancies." (PMID 35765406, 2022). "Somatic and germline alterations involving RUNX1 gene are commonly encountered in a variety of hematological malignancies." (PMID 32782381, 2021). "First, it is well known that alteration of each protein, RUNX1 and CBFA2T3, separately, causes hematological malignancies." (PMID 33743795, 2021). "Starting from 8 weeks after TMX induction, RUNX1-ETO mice died due to hematological malignancies, characterized by leukocytosis, anemia, thrombocytopenia, and hepatosplenomegaly." (PMID 34148054, 2021). "The clarification of in vivo roles of Runx1 in early myeloid cell development will shed new light on a better understanding of RUNX1-related hematological diseases." (PMID 33434583, 2021). "Some of these hub genes were either considered essential to the survival of AML cells (JMJD1C) or identified as fusion partners (CHD1) of the major player in hematologic malignancies (RUNX1)." (PMID 31988326, 2020). "This in vivo study aimed to establish a stable line of zebrafish expressing the human RUNX1-Evi-1 fusion gene under the control of a heat stress-inducible bidirectional promoter, and investigate its roles in hematopoiesis and hematologic malignancies." (PMID 26674644, 2015). "We found TCF7 binds to its own promoter and the promoter of Runx1 (Aml1), a developmental determinant in hematopoietic cells that is best known for its critical role in hematological malignancies." (PMID 22412390, 2012). "RUNX1-related thrombocytopenia, ETV6-related thrombocytopenia, and ANKRD26-related thrombocytopenia are three known hereditary thrombocytopenias with an established predisposition to hematologic malignancies." (PMID 41458504, 2025). "Notably, heterozygotes for germline P/LP variants in GATA2, ETV6, and RUNX1 (both cohorts), and DDX41 (UKBB only) have significantly increased risk for developing hematological malignancies." (PMID 39501104, 2025). "This indicates that RUNX1 has a dual effect on hematological diseases, depending on the species." (PMID 37697370, 2023). "It is conceivable that the association of RUNX-1 and miR-215-5p expression could also be a causative explanation for the loss of A/B antigen expression in RUNX-1 mediated hematological malignancies." (PMID 36854778, 2023).
hematological malignancies (continued). "Given that the patients with SCN are more prone to develop somatic RUNX1 mutations, SCN/AML has been recognized as an important model to further investigate the role of secondary RUNX1 mutations in the molecular pathogenesis of hematological malignancies." (PMID 35765406, 2022). "It is not surprising that RUNX1 dysfunction is associated with the development of IBMFSs and various hematological malignancies." (PMID 35765406, 2022). "And its meaning depends on the effect of RUNX1 in related clonal hematological diseases." (PMID 33663081, 2021). "Thus, dominant inhibition of RUNX1 function is considered a common, and necessary, alteration for the development of several hematological disorders." (PMID 26901859, 2016). "Therefore, RUNX1 loss sensitized cells to JAK inhibition, and targeted use of JAK inhibitors may be beneficial in treating RUNX1mut hematopoietic disease." (PMID 37581927, 2023). "Given that Runx1 has important functions in development and human disease, an increased understanding of dynamic cis-regulatory mechanisms underpinning its regulation will be vital to future efforts to develop potential therapeutic approaches to manipulate RUNX1 expression in human blood disorders." (PMID 35140205, 2022). "The Runt-related transcription factor 1 (RUNX1) gene is well-characterized in CBF-AML and other hematologic malignancies, and it is known to impact hematopoiesis." (PMID 37509244, 2023). "Therefore, the GFP silencing phenomenon was unlikely and we postulate that the small number of RUNX1-ETO expressing cells may cause hematological malignancies in a non-cell autonomous manner in the MPD cases." (PMID 34148054, 2021). "Along with RUNX1, FLI1 is also a critical regulator of embryonic hematopoiesis; thus, compensatory epigenetic downregulation of RUNX1 and FLI1 may be required for viable embryogenic development in DS, but potentially also results in increased risk of hematological malignancies." (PMID 33547282, 2021). "Apart from their functions in MK differentiation, RUNX1, GATA1 and c-MPL as well as other epigenetic factors such as BRD4 found in this study are dysregulated in a broad spectrum of hematological malignancies as well as solid tumors." (PMID 26575292, 2015). "RUNX1 abnormalities, occurring through either genetic or non-genetic mechanisms, are involved in the development of various hematological malignancies." (PMID 39151099, 2025). "Multiple chromosomal rearrangements involving ETV6 (such as ETV6::RUNX1, ETV6::ABL1, ETV6::NTRK3, and ETV6::ACSL6) have been demonstrated to play a crucial role in the development of several hematologic diseases such as AML, as well as in their diagnosis and prognosis." (PMID 39723366, 2024). "Thus, also in the absence of RUNX1 translocation or mutations, additional factors such as defects in the expression of NIPBL observed in AML patients might contribute to haematological diseases." (PMID 32323916, 2020). "Thus, also in the absence of RUNX1 translocation or mutations, additional factors such as defects in the expression of NIPBL might induce haematological diseases." (PMID 32323916, 2020). "For clinical application, our results raise the possibility that activators of CAR cell-specific RUNX1 can decrease bone marrow fibrosis, which might be applied to non-cell-autonomous therapies targeting the HSC niches, in hematological disorders, including MPN." (PMID 35551452, 2022).